SCD (stearoyl-CoA desaturase)
Diseases named in the same sentence as SCD in open-access papers (continued):
Sharing a sentence is not in itself a finding about the gene and the disease.
cancer (continued). "Cancer cells overcome this inhibition by increased expression of stearoyl CoA desaturase (SCD1) which is responsible for converting saturated fatty acids (SFAs) to monounsaturated fatty acids (MUFAs)." (PMID 34638293, 2021). "SCD catalyzes the biosynthesis of monounsaturated fatty acids, and its role in cancer has been previously reviewed." (PMID 33413672, 2021). "Collating our in vitro and in vivo data, this suggested that drug-induced FOSB induction is a potential mechanism of acquired resistance to SCD inhibitors in cancer." (PMID 33568479, 2021). "These other members of the desaturase family have received little recent attention from the cancer biology field compared to SCD (see review)." (PMID 33413672, 2021). "FOSB-driven acute phase response signaling and FOSB-mediated SCD transcription and perhaps FOSB/SCD-independent mechanisms are involved in SCD inhibitor acquired resistance in cancer." (PMID 33568479, 2021). "Stearoyl-CoA desaturase-1 (SCD1) is reported to play essential roles in cancer stemness among several cancers." (PMID 32350414, 2020). "In that case, the request and importance of elevated and activated lipogenic enzymes, including SCD-1, in the progression of cancer survival, metastasis and malignancy have hence been demonstrated." (PMID 32630668, 2020). "Although more researchers have started to explore the pharmaceutical role of SCD-1 in cancer therapy, it still needs more efforts to elucidate the precise regulatory mechanism in its expression level in cancer cells under different stimulations." (PMID 32630668, 2020). "SCD1 knockout mice are viable but present skin abnormalities and weight reduction suggesting that cancer treatments based on SCD inhibition should be restricted to a local and short action." (PMID 31936134, 2020). "SCD1 is overexpressed in diverse cancer types, while SCD also promotes liver fibrosis and tumor development in mice." (PMID 32947972, 2020). "Here, we studied the ability of two grape skin extracts (GSEs), Autumn Royal and Egnatia, to influence the cell motility and membrane fluidity regulated by the enzyme Stearoyl-CoA desaturase-1 (SCD1) which increases with the cancer aggressiveness." (PMID 32143529, 2020). "ACSL/SCD-1 pathway can regulate the invasiveness of cancer cells and serve as a predictor of survival." (PMID 30684960, 2019). "Recent evidence suggests that the rewiring in lipid metabolism, such as in the acyl-CoA synthetase/stearoyl-CoA desaturase network, promotes the migration and invasion of cancer cells through the epithelial-mesenchymal transition (EMT)." (PMID 30949448, 2019). "The authors observed a diversified sensitivity of cancer cells of a different origin (liver, lung, prostate, and breast) to the inhibition of SCD with Merck Frosst compound 3j." (PMID 31284458, 2019). "Many studies reported that pharmacologic or genetic interference with SCD remarkably accelerated the process of cellular apoptosis in different types of cancer." (PMID 30592142, 2019). "The relation between cancer mortality and activity of SCD-1, estimated on the basis of serum cholesteryl ester ratio of 16:1 n-7 and 16:0, and presence of a single nucleotide polymorphism in its gene, suggests that endogenous synthesis of MUFAs may exert an effect on cancer outcome." (PMID 30684960, 2019). "In this murine model, the overexpression of ACSL4 is preserved, probably indicating a predominant role of this ACSL/SCD component in cancer progression aspects." (PMID 31339921, 2019). "SCD or PI3 expression was significantly up‐regulated in cancer tissue compared to that in non‐tumour tissue." (PMID 30592142, 2019).
cancer (continued). "Cancer cells use this pathway when SCD-1 is inhibited, underscoring the metabolic plasticity of cancer cells for making their own lipids for growth and resistance to therapy." (PMID 31142021, 2019). "Key enzymes related to fatty acid synthesis, such as FAS, ACC and SCD, are highly expressed in many cancer cells." (PMID 30821074, 2019). "The expression level of fatty acid desaturase 2 (FADS2), an enzyme converting palmitate to sapienate, correlated with the independence of cancer cells from SCD." (PMID 31284458, 2019). "Over the last few years, several SCD-1 inhibitors have demonstrated their effectiveness in different preclinical in vitro and in vivo models of cancer, by specifically targeting stemness-related properties." (PMID 30967773, 2019). "Up-regulation of the MUFA synthesis enzyme, SCD, has been observed in several types of human cancers, and its gene expression is correlated with the malignant transformation of cancer and poor survival rates." (PMID 30949448, 2019). "They showed that some types of cancer cell are insensitive to modifications of SCD and continued to grow implicating a second enzyme FADS2." (PMID 31717414, 2019). "Key regulators of lipogenesis—SREBPs, acetyl-CoA carboxylase (ACC), fatty acid synthase (FASN), and stearoyl-CoA desaturase 1 (SCD1) —are significantly up-regulated in various human cancers." (PMID 29784041, 2018). "Over the past decade, numerous papers have implicated the gene expression and enzyme activity of stearoyl-CoA desaturase 1 (SCD1) in the pathogenesis of cancer." (PMID 29396722, 2018). "Met downregulated expression of enzymes of fatty acid de novo synthesis, such as ATP Citrate Lyase (ACLY), Fatty Acid Synthase (FAS), Fatty Acyl-CoA Elongase 6 (ELOVL6), and Stearoyl-CoA Desaturase-1 (SCD1) in cancer cells." (PMID 28230778, 2017). "The proto-oncogene c-myc is overexpressed in the majority of human cancers, while increased expression of SCD-1, and to a lesser extent SCD-5, has also been found in many solid tumors and associated with poor prognosis of survival." (PMID 28452935, 2017). "The role of SCD in cancer cell proliferation and survival has been established using different cancer cell lines." (PMID 28286737, 2017). "Silencing of SCD reduced the ability of cancer cells to grow as spheroids, indicating that these conditions restrict the access to exogenous lipids making cancer cells dependent on SCD function." (PMID 27042297, 2016). "In summary, our results demonstrate that SCD is an important enzyme to support the enhanced de novo lipid synthesis and desaturation in cancer cells under conditions where exogenous lipids are limiting." (PMID 27042297, 2016). "Here, we show that cancer cells are highly dependent on stearoyl-CoA desaturase (SCD), the enzyme that introduces a double bond at the Δ9 position of newly synthesised FAs." (PMID 27042297, 2016). "Together, these results implicate SCD in growth and survival of cancer cells under serum-deprived conditions." (PMID 27042297, 2016). "The sensitivity of cancer cells towards SCD inhibition was greatly increased by spheroid culture, a condition that recapitulates nutrient and oxygen gradients found in tumours." (PMID 27042297, 2016). "Sub-lethal doses of SCD inhibitor also increased the sensitivity of cancer cells towards chemotherapeutic agents and inhibitors of mitochondrial respiratory complexes." (PMID 27042297, 2016). "Taken together, our results highlight the importance of SCD for lipid provision in cancer cells under the metabolically compromised conditions that are likely to be encountered within the tumour microenvironment." (PMID 27042297, 2016). "SCD controls the production of lipid species that are important for cell viability and determine the sensitivity of cancer cells towards chemotherapeutic agents." (PMID 27042297, 2016). "Our study further demonstrates that the dependence of cancer cells on SCD is strongly determined by the availability of exogenous lipids." (PMID 27042297, 2016).
cancer (continued). "Stearoyl-CoA-desaturase (SCD1) is a key enzyme in unsaturated fatty acids metabolism, whose expression is related to cancer progression." (PMID 27566559, 2016). "We also confirmed that the effect of SCD silencing on cancer cell viability was due to inhibition of enzymatic activity, as two structurally unrelated inhibitors of SCD activity showed comparable efficacy in reducing proliferation and survival in cancer cells." (PMID 27042297, 2016). "Taken together, this work indicates that changes in SCD expression such as those seen in cancers and metabolic disorders would have important consequences to membrane function." (PMID 26528916, 2015). "Stearoyl-CoA desaturase-1 (SCD-1) catalyzes the production of monounsaturated fatty acids that are essential for membrane biogenesis, and is required for cell proliferation in many cancer cell types." (PMID 26022099, 2015). "Previous studies have indicated that SCD1 (one isoform of SCD) played an important role in cancer progression." (PMID 26061164, 2015). "Screening for small molecules which completely inhibit human SCD activity would be critical for successful therapeutic action against SCD in cancer treatment." (PMID 24069385, 2013). "Studies in cancer cells showed that SCD activity controls the passage of cycling cells through the G1 phase into S phase." (PMID 24212819, 2011). "The relevance of SCD activity in defining the fatty acid composition in cancer cells was further exposed by the finding that the inhibition of SCD1 expression/activity leads to a marked decrease in MUFA in cancer cell lipids." (PMID 24212819, 2011). "And in agreement with the observed decrease in lipogenesis, the blockade of SCD activity resulted in increased phospho-AMPK in both cancer cell lines as well as in an increase in phospho-ACC in H1299 cells treated with the SCD inhibitor." (PMID 19710915, 2009). "The expression of SCD1, the main SCD isoform, is increased in several human cancers, chemically induced tumors, as well as in oncogene-transformed cells." (PMID 19710915, 2009). "We also report that pharmacological inhibition of SCD activity drastically reduced cellular proliferation in cancer cells, confirming that SCD1 activity is a crucial requirement for cancer cell growth." (PMID 19710915, 2009). "This confirms that CVT-11127 is highly effective at suppressing the very high SCD activity found in these cancer cell lines." (PMID 19710915, 2009). "Furthermore, we observed significant increases in ROS levels in both cancer cell lines and reductions in the levels of the lipogenic enzyme, stearoyl-CoA-desaturase 1 (SCD1)." (PMID 42015465, 2026). "Moreover, MUFA in a high quantity, promoted by SCD activity, is protective against it, promoting cancer cell proliferation and survival." (PMID 41301494, 2025). "Stearoyl-CoA desaturase (SCD), an enzyme regulating membrane fluidity by desaturating fatty acids, is implicated in tumorigenesis, but resistance to its inhibition presents a challenge in cancer therapy." (PMID 40565099, 2025). "Thus, SCD plays a central role in lipid homeostasis and has emerged as a promising therapeutic target in cancer." (PMID 41383134, 2025). "Combining SCD inhibitors with cisplatin may suppress the proliferation and metastasis of cancer cells through synergistic effects and improve the anti-tumor effects of cisplatin." (PMID 39757995, 2025). "Subsequent studies have also found that combination therapy with death-inducing drugs (such as sorafenib and cisplatin) and SCD blockade may become a new strategy for cancer treatment." (PMID 41421797, 2025). "The expression of SCD-1, is significantly upregulated and contributes to the progression of cancer." (PMID 38994204, 2024). "SCD-induced mitochondrial fatty acid oxidation is necessary to supply the energy in cancer cells." (PMID 39543650, 2024). "Thus, TME hypoxia reduces SCD activity and constrains the ability of cancer cells to maintain a balance between unsaturated and saturated fatty acids." (PMID 39284708, 2024).
cancer (continued). "As for other components of the TME, we found that SCD was mainly overexpressed in malignant tumor cells, endothelial cells, fibroblast cells, and macrophage cells, whereas it was relatively low for the immune cell components of CD4 Tconv cells, natural killer cells, B cells, and neutrophils." (PMID 38905386, 2024). "In addition, as MUFAs are critical for cell growth, highly proliferating cancer cells depend on SCD expression and its pharmacological inhibition reduces cancer cell growth." (PMID 39009641, 2024). "Furthermore, the translational expression level of SCD in pan-cancer was investigated on the HPA platform." (PMID 39351232, 2024). "This is demonstrated by the significant overexpression of SCD in various types of cancer." (PMID 39351232, 2024). "SCD plays a pro-tumor role in cancer cells by enhancing stemness, EMT, and chemoresistance." (PMID 39543650, 2024). "Therefore, SCD emerges as a potential target for cancer therapy, exhibiting robust anti-cancer effects in both in vivo and in vitro models, and showing promise in the realm of overcoming drug resistance." (PMID 39351232, 2024). "SCD is significantly increased in tumors and SCD-mediated desaturation of FA may represent an important step for cancer cell survival." (PMID 38541630, 2024). "Additionally, several genes exhibited significant expression differences across cancers, such as SCD and ASAH1, downregulated in LUAD but upregulated in other cancers." (PMID 39393173, 2024). "Therefore, inhibiting SCD functions has been proposed as a therapeutic strategy for some types of cancer." (PMID 39351232, 2024). "Stearoyl-CoA desaturase 1 (SCD1) is an attractive target for cancer therapy." (PMID 38849435, 2024). "Consequently, the role of SCD as a potential therapeutic target in cancer treatment has gained attention due to its pivotal involvement in tumor lipid metabolism and membrane architecture." (PMID 39431237, 2024). "WNT signaling in cancer stem cells (CSCs) may be supported by MUFAs synthesized due to the increased activity of stearoyl-CoA desaturase 1 (SCD1)." (PMID 39062964, 2024). "Increased expression and activity of stearoyl CoA desaturase (SCD1), i.e., the enzyme converting saturated fatty acids to Δ9-monounsaturated fatty acids, is involved in increased cancer cell proliferation, growth, migration, EMT, metastasis, and chemoresistance and maintenance of cancer stem cells." (PMID 37048080, 2023). "All three enzyme families involved in FA synthesis (ACC, FASN, SCD) are frequently up-regulated in several cancer types, including glioblastoma, breast, ovarian, lung, prostate and liver cancer; furthermore, their expression correlates with poorer prognosis and high cancer grade." (PMID 36839759, 2023). "A previous study showed that SCD protects cells from ferroptosis through desaturating fatty acids and tumor endothelial cell-derived fatty acid binding protein 4 to enhance lipid droplet formation in cancer cells." (PMID 37051693, 2023). "SCD was found to be overexpressed in multiple cancers and corresponds to decreased cell survival." (PMID 37046804, 2023). "However, accumulating evidence suggested that KRAS mutant cancer cells bypass sensitivity to SCD inhibition by scavenging unsaturated fatty acids from lysophospholipids." (PMID 36675307, 2023). "SCD levels are positively correlated with cancer aggressiveness and chemoresistance." (PMID 36472914, 2023). "SCD is involved in the anti-tumour T-cell response of various cancer types." (PMID 36763105, 2023). "Our observations, in conjunction with previous studies, suggest that the two SCD isoforms might play separate roles in the mechanisms of cancer." (PMID 36980176, 2023). "Importantly, treatment with the SCD-specific inhibitor MF438 efficiently blocked the CES1 effect on HCC apoptosis, further highlighting the key role of SCD in CES1-mediated cancer cell growth." (PMID 36472914, 2023).
cancer (continued). "Furthermore, SCD participates in mediating the inflammatory reaction, which promotes the progression of cancer." (PMID 37293508, 2023). "Indeed, the desaturase enzyme known as stearoyl-CoA desaturase (SCD-1), carrying out the transformation of stearic acid to oleic acid, is crucial for cancer development and invasiveness." (PMID 35053341, 2022). "However, SCD is overexpressed in multiple human cancers, and SCD upregulation can increase cancer cell motility and membrane fluidity and promote metastasis and invasion 28, 29, which appears to be in conflict with our finding." (PMID 35342344, 2022). "Stearoyl-CoA desaturase (SCD)-dependent fatty acid desaturation is the most common way to desaturate fatty acids although some studies have shown that cancer cell lines may activate other desaturation pathways." (PMID 36038892, 2022). "Moreover, the CAF-derived OA enhanced cancer cell stemness via upregulation of SCD and downstream signaling pathways in In vitro and In vivo models." (PMID 36514170, 2022). "Increased expression of SCD is correlated with cancer aggressiveness and poor outcomes in patients." (PMID 35370706, 2022). "By doing so, SCD-independent cancer cells evade the growth inhibitory effect of SCD inhibition." (PMID 35954376, 2022). "The previous study indicated that upregulation of SCD could proliferate cancer cells in a lipid-depleted environment for it could synthesize monounsaturated fatty acids." (PMID 36131793, 2022). "Furthermore, various cancer cells resistant to pharmacological SCD inhibition have been shown to utilize an alternative FA desaturase pathway that produced cis-6 SFA(16:0) (sapienic acid)." (PMID 35954376, 2022). "Stearoyl CoA desaturase is another important enzyme involved in lipid metabolism in cancer cells." (PMID 35631131, 2022). "Notably, most cancer cells contain a high SCD activity to demand an even higher particular lipogenesis to support the rapid growth and de novo synthesis of membranes." (PMID 36140684, 2022). "However, metabolic plasticity in fatty acid desaturation, exemplified by the desaturation of palmitate to sapienate, was recently highlighted as a means of evading SCD‐targeted therapies in cancer cell lines." (PMID 35560527, 2022). "Furthermore, the increased SCD expression augments stemness of cancer cell through actin-polymerization and subsequent YAP nuclear translocation." (PMID 36514170, 2022). "Moreover, our xenograft model using cancer cell subclones with manipulated SCD expression also supported the role of SCD in the maintenance of CSC properties." (PMID 36514170, 2022). "In addition, stearoyl-CoA desaturase (SCD1) is a lipid-modifying enzyme that promotes monounsaturated fatty acid synthesis and protects cancer cells from ferroptosis." (PMID 36147464, 2022). "Likewise, several studies reported an upregulation of SCD in several cancers and its implication in cell proliferation, migration, and metastasis during both early states and progression." (PMID 35406721, 2022). "Therefore, it is possible that CTS modulates lipid and fatty acid metabolism in resistant cancer cells by regulating the SCD and AMPK pathways." (PMID 35370706, 2022). "Furthermore, SCD is a target of interest in cancer because it is upregulated because of high lipogenic and MUFA demand (from increased metabolic activity and division; Tracz-Gaszewska and Dobrzyn, 2019)." (PMID 34301719, 2021). "Because all of the SCD-high lines were sensitive and the SCD-low lines were resistant, our data demonstrate that at least in GBM and perhaps other human cancers, SCD expression could be a determining factor during patient selection for SCD inhibitor therapy." (PMID 33568479, 2021). "Importantly, MYC has been implicated as a mediator of both RAS and BCR-ABL-driven cancers and is shown to directly influence gene expression of ACACA, FASN, and SCD." (PMID 34399819, 2021). "SCD overexpression in cancer cells alters membrane fatty acid composition." (PMID 33568479, 2021).